KCTD21 (potassium channel tetramerization domain containing 21)
Description:
Probable substrate-specific adapter of a BCR (BTB-CUL3-RBX1) E3 ubiquitin-protein ligase complex mediating the ubiquitination and subsequent proteasomal degradation of target proteins. Promotes the ubiquitination of HDAC1. Can function as antagonist of the Hedgehog pathway by affecting the nuclear transfer of transcription factor GLI1; the function probably occurs via HDAC1 down-regulation, keeping GLI1 acetylated and inactive. Inhibits cell growth and tumorigenicity of medulloblastoma (MDB).
Synonyms: KCASH2
Tractability: No criterion of Open Targets' tractability assessment is met for any kind of drug.
Gene: Protein-coding gene on chromosome 11 (78,171,245 to 78,188,644, reverse strand). Ensembl gene ENSG00000188997.
Subcellular location (Human Protein Atlas): Cytosol
Gene Ontology:
Molecular function: cullin family protein binding; histone deacetylase binding; identical protein binding; protein binding
Biological process: negative regulation of smoothened signaling pathway; ubiquitin-dependent protein catabolic process; protein homooligomerization; protein ubiquitination
Genetic constraint (gnomAD): Loss-of-function variants: 9 observed, 13.97 expected, observed/expected ratio (o/e) 0.64, 90% interval 0.39 to 1.12. The upper end of that interval is the gene's LOEUF score, 1.12, which puts it in group 4 of 6, group 1 being the genes least tolerant of losing a copy. Missense variants: 303 observed, 353.98 expected, observed/expected ratio (o/e) 0.86, 90% interval 0.78 to 0.94. Synonymous variants: 142 observed, 145.18 expected, observed/expected ratio (o/e) 0.98, 90% interval 0.85 to 1.12.
Homologues: Orthologues: chimpanzee KCTD21 (100% identical), mouse Kctd21 (99% identical), pig KCTD21 (99% identical), dog KCTD21 (99% identical), guinea pig KCTD21 (99% identical), macaque KCTD21 (99% identical), rat Kctd21 (98% identical), rabbit KCTD21 (98% identical), Drosophila melanogaster twz (23% identical), Caenorhabditis elegans F32B4.5 (16% identical). Paralogues in human: KCTD11 (43% identical), KCTD6 (33% identical), KCTD4 (26% identical), KCTD15 (25% identical), KCTD8 (25% identical), KCTD1 (24% identical), KCTD19 (24% identical), KCTD16 (23% identical), KCTD12 (23% identical), KCTD18 (22% identical), KCNRG (22% identical), KCTD7 (22% identical), and 1 more.
Diseases named in the same sentence as KCTD21 in open-access papers:
KCTD21 is named in the same sentence as 8 diseases in open-access papers, as found by Europe PMC text mining. Sharing a sentence is not in itself a finding about the gene and the disease. The quoted sentences say what the papers report.
breast carcinoma (2 papers, 2010 to 2018). "In ERBB2-amplified breast cancer, expression of KCTD21 (Potassium Channel Tetramerization Domain Containing 21) was related to genomic copy number alterations." (PMID 30618566, 2018). "GISTIC identifies a peak encompassing four genes (THRSP, NDUFC2, ALG8 and KCTD21), amplification of which have been shown in breast cancer to correlate with over-expression and poor survival." (PMID 20844748, 2010).
Intellectual disability (1 paper, 2017). "Examples include SUMF1, KDM5B and MXRA5 (Known-ASD genes), PRODH2 and KCTD21 (implicated in schizophrenia), as well as USP9X and SMS (implicated in intellectual disability)." (PMID 28720891, 2017). "Examples include PRODH2 and KCTD21 (implicated in schizophrenia), USP9X and SMS (implicated in intellectual disability), TRIM9 and KDM5B (known-ASD genes), and others such as AGL and MOGS (candidate genes involved in energy metabolism and immune responses, respectively)." (PMID 28720891, 2017).
lymph node metastasis (1 paper, 2022). "Subsequently, we analyzed the correlation between KCTDs gene expression level and clinicopathologic features, and we found that the expression of KCTD5 and KCTD21 was significantly higher in the lymph node metastasis group than in the normal group." (PMID 35705627, 2022).
cancer (1 paper, 2025). A tumor composed of atypical neoplastic, often pleomorphic cells that invade other tissues. "However, the associations of KCTD2, KCTD15, and KCTD21 with cancer progression remain underexplored, making our findings novel and significant." (PMID 40832836, 2025). "Emerging evidence has highlighted the significance of various gene families in cancer progression, including the KCTD family, comprising genes, including KCTD2, KCTD5, KCTD9, KCTD10, KCTD12, KCTD15, KCTD16, and KCTD21." (PMID 40832836, 2025).
KCTD21 also shares sentences with these, for which no sentence is quoted: medulloblastoma (4 papers); tumor (4); colon cancer (1); schizophrenia (1).